KIF23 (kinesin family member 23)
Diseases named in the same sentence as KIF23 in open-access papers (continued):
Sharing a sentence is not in itself a finding about the gene and the disease.
cancer (continued). "KIF23 plays a crucial role in the tumorigenesis and cancer progression." (PMID 35524313, 2022). "KIF23 has been proven to promote cell proliferation in many cancer cells." (PMID 35457254, 2022). "In addition, ANLN expression was strongly associated with that of DEPDC, KIF14, KIF23, RACGAP1, and CKAP2L genes across cancers." (PMID 35340220, 2022). "Some studies have found that KIF23 has a role in regulating cell proliferation in various cancer, so we speculate that KIF23 may regulate the proliferation of PASMCs in PAH." (PMID 35457254, 2022). "Several studies showed KIF23 plays an oncogenic role in several cancer types." (PMID 35524313, 2022). "All these studies indicated that KIF23 plays as an oncogene in cancers." (PMID 34017355, 2021). "Downregulating the expression of KIF23 inhibits the formation of mesosomes and cytokinesis, which results in cell division defects and the formation of multinucleated cells, ultimately leading to cancer 7,30." (PMID 33754001, 2021). "Several studies have shown that KIF23 plays a crucial role in cancer." (PMID 33754001, 2021). "It seems that elevated of KIF23 expression is a common event in various human cancers." (PMID 34017355, 2021). "KIF11, KIF15, and KIF23 are overexpressed in several cancer types." (PMID 32642733, 2020). "The protein levels of CHEK1 and MCM10 were more significant in carcinomas than normal tissues and the differential expressions of KIF23 and TTK could be observed between primary lesions and liver metastases." (PMID 33134313, 2020). "Similarly, by regulating mitogenesis, KIF23 can influence cancer cell proliferation." (PMID 35669725, 2022). "Furthermore, we explore the KIF23 CNVs in Pan-cancer levels from TCGA datasets." (PMID 34017355, 2021). "However, to date, the mechanisms of KIF23 in cancer remain unknown." (PMID 32365332, 2020). "Several proteins involved in cytoskeleton rearrangement such as actin, TNS3, KIF23, CKAP2L, NEDD9 and PLEC were also hyperphosphorylated, indicating the known regulatory role of AXL in promoting cancer cell migration/invasion and inducing epithelial-mesenchymal transition (EMT)." (PMID 34439388, 2021).
KIF23 also shares sentences with these, for which no sentence is quoted: infection (11 papers); pancreatic cancer (5); clear cell renal cell carcinoma (3); cryptococcosis (3); systemic candidiasis (3); Anaplastic Thyroid Carcinoma (2); diffuse large B-cell lymphoma (2); mesothelioma (2); triple-negative breast carcinoma (2); adenovirus infection (1); blood cancer (1); brain cancer (1); breast tumor (1); chronic myeloid leukemia (1); ciliopathy (1); CNS tumors (1); familial hypercholesterolemia (1); gallbladder carcinoma (1); lung squamous cell carcinoma (1); lymphoma (1); malaria (1); meningioma (1); metastatic tumours (1); mucinous ovarian carcinoma (1); neuroblastoma (1); oligoastrocytoma (1); oligodendroglioma (1); omphalocele (1); pleural mesothelioma (1); pulmonary fibrosis (1).
A further 10 diseases each share a sentence with KIF23 in 1 paper.